CD4 (CD4 molecule)
Diseases named in the same sentence as CD4 in open-access papers (continued):
Sharing a sentence is not in itself a finding about the gene and the disease.
cancer (continued). "However, immunosurveillance promotes the selection of poorly immunogenic cancer cells through cancer immunoediting where neoplastic cells that resist the elimination phase can persist in equilibrium with effector CD4+ and CD8+ T cells under a pro-inflammatory milieu." (PMID 30042343, 2018). "Low CD4 cell counts could not be attributed to specific medical conditions, nor use of immunosuppressive drugs, in most virus-associated cancer cases in the study cohort." (PMID 30315476, 2018). "CD4+ T cell antitumor responses have mostly been studied in transplanted tumors expressing secreted model antigens (Ags), while most mutated proteins in human cancers are not secreted." (PMID 29844317, 2018). "Therefore in models in which CD4 T cells promote cancer development, one may expect a different consequence of targeted mutation of the Cd24 gene." (PMID 29423273, 2018). "In fact, the CD4+ CD25+ Foxp3+ Tregs subpopulation may exert a critical role in cancer promotion." (PMID 29375559, 2017). "Therefore, developing approaches to prevent CD4+CD25+FOXP3+ Treg elevation with age may enhance T-cell-mediated immune response and further reduce the risk of cancer." (PMID 28253320, 2017). "Although the link between cancers and Treg induction has been previously investigated in murine studies, it has not been conclusively demonstrated in human cancers, wherein conventional CD4 T cells have been used, consisting of both naïve and memory populations." (PMID 28239749, 2017). "The evaluation of regulatory T (Treg) (CD4+CD25high CD127neg) lymphocyte count with respect to the T helper (TH) (CD4) number has been shown to represent the main immune parameters capable of signifying the functional status of the anticancer immunity in cancer patients." (PMID 29312592, 2017). "In our cohort, a CD4+/CD8+ ratio of greater than 1 was associated with better survival in the overall and epithelioid groups and this parameter warrants further analysis in other cancers to determine if it might be a useful prognostic marker for survival." (PMID 28817839, 2017). "Indeed, the efficacy of cyclophosphamide is partly due to intestinal bacteria, against which the host becomes immunized during the treatment, accumulating anti-commensal effector pTh17 and memory Th1 CD4+ T cells, which are necessary for the anti-cancer effect." (PMID 28404796, 2017). "However, CD62L expression on leukocytes is highly susceptible to freeze-thaw damage and there is the suggestion that CD62L expression on CD4+ T cells is associated with a Th2 cytokine profile rather than preferred Th1 profile for cancer immunotherapy." (PMID 28239467, 2017). "The overall average of the chemokine receptor expression frequencies showed that the T lymphocytes isolated from carcinoma tissues expressed lower levels of chemokine receptors (20.1 ± 5.6%) than those isolated from unaffected mucosa (26.9 ± 5.8%) (Wilcoxon test; p < 0.01) in CD4+ lymphocytes." (PMID 29020986, 2017). "Moreover Tregs are involved in the inhibition of effector functions in both inflammation and cancer; it has been shown that the presence of CD4+CD25+FOXP3+ regulatory T cells in cancer tissues is associated with mechanisms of tumor immune escape and worse prognosis." (PMID 27323400, 2016). "For some of these cancers, anti-Her-2/neu treatment has become an essential part of the therapy A Phase I study showed that vaccination with Her-2/neu peptides could induce a strong and long lived CD4 and CD8 specific response." (PMID 27323861, 2016). "The negative correlation also found between the plasma concentrations of IL-1β and numbers of CD4+NKG2D+ T cells in cancer patients may simply be an independent variable resulting from the fact that IL-1β is typically activated in situations where TNF-α is produced." (PMID 26486970, 2015). "Hence, previous studies demonstrated that CD4 T cells could be involved in the efficacy of many cancer immunotherapies." (PMID 26350591, 2015).
cancer (continued). "Deficiency of CD4+ T helper (CD4+ Th) cell numbers and/or functionality, which are usually needed to optimize CD8+ T cell responses, has further dampened hope for the generalized effectiveness of conventional vaccine strategies in the vast majority of cancer patients." (PMID 25941586, 2014). "Moreover, the status of C/EBPα does not affect the accumulation of PD1+ CD4+ T cells during leukemic progression and it does not affect the susceptibility to cancer." (PMID 24404186, 2014). "Notably, patients with NADCs had a better immunological status than patients with ADCs at the time of cancer diagnosis with statistically significant higher nadir and CD4+ T-cell counts, indicating that patients with NADC appeared to have inferior survival despite better immunity." (PMID 24760049, 2014). "Although we do not know the mechanistic basis of our observation related to the requirement for CD4+ T cell help for the generation of therapeutic primary immune responses against cancer, it is tempting to speculate that CD4+ T cells may facilitate vaccine efficacy by several means." (PMID 24066030, 2013). "The improved survival in recent years may reflect an increased use of cancer treatment in HIV-positive patients, as well as the availability of improved ART regimens leading to greater CD4 count increases, and a reduction in cancer risk behaviour (e.g. increased smoking cessation)." (PMID 24106926, 2013). "The CTLA-4 60G/A polymorphism is a key susceptibility locus for autoimmune and cancer, previous results indicated that presence of G alleles in polymorphic sites 60G/A polymorphism was associated with lower levels of membrane and cytoplasmic CTLA-4 in CD4+ T lymphocytes." (PMID 24376736, 2013). "Although not demonstrated in our study, it is probable that in other forms of immunotherapy such as cancer vaccines, there could be additional benefits of CD4 cells based on their capacity to act on dendritic cells and promote CD8 expansion, function, and memory induction." (PMID 23717511, 2013). "Alternatively, CD4+ TReg cells may possess other underappreciated anti-cancer functions." (PMID 23533029, 2013). "Thus, the intention here is to re-establish the role of the acquired immune response (that is: specific antigen presentation, stimulation of antigen-specific CD4+ T helper (TH) cells and generation of antigen-specific effector cells) as the major mechanism of defence against cancer." (PMID 22849661, 2012). "Thus it is possible to create a vault nanocapsule vaccine that can result in the unique combination of immunogen-responsive CD8+ and CD4+ T cell immunity coupled with an IgG1 response for future development of vault nanocapsule-based vaccines against antigens for human pathogens and cancer." (PMID 22808011, 2012). "We detected a significant downregulation of CD127 mRNA expression in CD4+CD25high T cells from healthy donors (n = 5) as well as CLL patients (n = 5, P < 0.05) by quantitative PCR indicating that CD127 expression might also be used to specifically identify CD4+FOXP3+ Treg cells in cancer patients." (PMID 21904560, 2011). "Therefore CD4 T cell help is clearly a critical component of immune responses to cancer." (PMID 22046294, 2011). "Moreover, CXCL16 enhanced the growth of CXCR6-expressing cancer and primary CD4 T cells." (PMID 19690611, 2009). "Therefore, it can bepostulated that Tregs can impair antitumor immune responses in cancer patients.In addition to naturally occurring CD4+CD25+ Tregs, also IL-10 producing Tr1cells have been demonstrated to contribute to ineffective antitumor immuneresponses in cancer patients." (PMID 18317534, 2007).
cancer (continued). "Secondary outcomes included immune function (CD4+, CD8 + counts, CD4+/CD8 + ratio), hematological parameters, cancer-related fatigue (PFS), self-care ability (ESCA), quality of life (GQOLI-74), adverse reactions (CTCAE 5.0), and nursing satisfaction." (PMID 41987783, 2026). "CD8+ and CD4+ TRM are unique to MPE, similar to previous reports of TRM in ascites and pleural fluid from patients with various malignant tumours." (PMID 41574275, 2026). "Mph), which promotes CD4+ T cell accumulation via CXCL10/CXCR3 for HLA-DR+ Schwann cells and assists them in shaping the cancer-neuron-immune niche and facilitating HNSCC progression." (PMID 42295734, 2026). "CD4+ T cells are well known to support CD8+ T cell function, as demonstrated in numerous studies on chronic infection and cancer." (PMID 41484912, 2026). "In our analysis, DCAF7 expression showed robust positive associations with the infiltration of multiple immune subsets – including B cells, endothelial cells, macrophages, NK cells and both CD4+ and CD8+ T lymphocytes – across cancers." (PMID 41472554, 2026). "Our work underscores the possibility of utilizing CD4+ T cells, CD73, and cancer plasticity as predictive criteria for responsiveness to immunotherapy." (PMID 42118667, 2026). "The cross-linking of T cells to cancer cells mediated by the SadP-scFv UCHT1 lectibody resulted in T cell activation, both CD4+ and CD8+." (PMID 41333282, 2026). "The data and the knowledge base generated in this study will pave the way for exploring the therapeutic potential of CD4-CTL effectors in a variety of diseases including infectious diseases, autoimmune disorders, and cancers." (PMID 41499515, 2026). "In particular, MKI67 expression were most positively correlated with Th1 and Th2 CD4+ T cells across various cancer types, while MKI67 expression were largely negatively correlated with Macrophage M2 cells across various cancer types." (PMID 40070823, 2025). "Flow cytometric analyses of T cells from the different culture conditions showed similar frequencies of CD4+ and CD8+ T cells independently of the culture format or presence of MCF-7/Luciferase cancer cells." (PMID 40240529, 2025). "To date, CARs have been predominantly applied in the context of CD4+ and/or cytolytic CD8+ conventional T cells for cancer therapy." (PMID 40955314, 2025). "PD-L1 is present on cancer cells and various types of immune cells including APC and naïve CD4 T cells and its presence directly reduces the cytotoxic effect of T lymphocytes." (PMID 40416959, 2025). "In the older cohort with TNBC, cancer basal cells showed the strongest predicted interactions with CD8+ T cells, CD4+ T cells and macrophages." (PMID 41188599, 2025). "In cancer immunotherapy, PD-1 blockade predominantly enhances CD8+ T cell responses, whereas CTLA-4 inhibition primarily affects CD4+ T cells." (PMID 40303350, 2025). "These lymphoid structures were also positive for follicular markers CD21 and CD23 and contained Bcl6+CD4+ TFH cells, which are all characteristics of mature TLS in human cancers, distinct from immature lymphocyte aggregates." (PMID 40897896, 2025). "The improved CD4+/CD8+ ratio also underscores the immune-enhancing effects of Huaier, indicating better immune regulation, an essential factor in controlling cancer and preventing its spread." (PMID 40573279, 2025). "Consistent with T cell-induced killing of cancer cells, the number of normal human splenic CD8+ > CD4+ T cells was significantly increased in the GlyTR-treated mice." (PMID 41005308, 2025). "This process was inhibited by treatment with the PI3 kinase and actin polymerization inhibitors wortmannin and latrunculin A, respectively, which suggested that the acquisition of CD4 and CD45 by cancer cells occurs via trogocytosis." (PMID 39741180, 2025). "GLUT1 plays a crucial role in maintaining CD4+ T-cell activation and is a marker of poor prognosis in HIV infection and cancer." (PMID 40149968, 2025).
cancer (continued). "In this study, we developed a prediction model for the “inflammation-cancer transition” using six predictors: ARG2, HSP90AA1, EZH2, ICAM1, macrophage M1, and activated CD4 memory T cells." (PMID 40352921, 2025). "In the present study, the frequency of CD57+CD4+ and CD57+CD28−CD27−CD4+ T cells were compared among the healthy donors, benign tumors, and malignant tumors." (PMID 40870871, 2025). "The main components of cancer immune surveillance include CD8-positive (CD8+) cytotoxic T cells, CD4-positive (CD4+) T helper cells, and dendritic cells." (PMID 40004836, 2025). "Adaptive immunity involves antigen‐presenting cells (APC) like DCs, which capture antigens on cancer cell surfaces and present them to CD8+ T cells and CD4+ T cells through major histocompatibility complex (MHC)‐I class and MHC‐II class pathways." (PMID 40547943, 2025). "It is possible that CD4+ T28zT2 T cells recognized cancer cells via NKG2D, formed immunological synapses, and delivered IFN-γ and Granzyme B specifically to cancer cells through the immunological synapses." (PMID 40107245, 2025). "CD4+FOXP3+ Treg cells maintain self tolerance, suppress the immune response to cancer, and protect against tissue injury during acute inflammation." (PMID 40100289, 2025). "Third, predicted interaction between CD55 expressed by CAFs, basal cancer cells and monocyte/macrophages and the adhesion G protein-coupled receptor E5 (CD97) gene, ADGRE5, on CD4+ T cells was higher with age." (PMID 41188599, 2025). "The unique capacity of saponins to induce potent cellular immune responses, including those mediated by CD4+ helper T cells and CD8+ cytotoxic T lymphocytes, in addition to humoral immunity makes them good candidates for use as adjuvants in cancer vaccines." (PMID 40333256, 2025). "In the TME, Th1, and Th9 subsets of CD4+T-cells enhance CD8+T-cell antitumor activity through cytokines like IL-2, IFN-γ, and IL-9, correlating with improved outcomes across cancers." (PMID 40260236, 2025). "A detailed investigation of their involvement in processes related to B cells and CD4+ T cells revealed that dendritic cells and macrophages were consistently correlated with MALAT1, FENDRR, FUS, and CRNDE across multiple cancers." (PMID 40728857, 2025). "T cells, including CD4+ and CD8+ subsets, play crucial roles in regulating adaptive immunity against cancers and identifying and eliminating cancer cells." (PMID 40547943, 2025). "CD4+ T cells modulate the immune response against infections, while CD8+ T cells are capable to eliminate cancer cells or cells infected with viruses or bacteria." (PMID 39717874, 2025). "A clinical cancer study found that, in the acupuncture group, CD3+ T and CD4+ T cell levels increased, while IL-6 and CRP levels decreased." (PMID 40098703, 2025). "From a cellular and mechanistic perspective, provided evidence that CD4+ T cell help is essential for CD8+ T cell function in chronic infection and cancer, justifying the use of AI to simulate complex immune cell interactions." (PMID 40756816, 2025). "The top three features from the primary tumors were the B cell / NK cell ratio in the cancer core, the density of CD68 macrophages, and the proportion of CD4+ T cells positive for Vimentin." (PMID 39975273, 2025). "The results showed that the expression levels of CD3, CD4, CD8, CD20 and IL-1β in the cancer nest were all increased after two recurrences, indicating that the immune cell infiltration was increased and the immune microenvironment was effectively activated." (PMID 40661951, 2025). "our findings revealed strong positive correlations between UCK2 expression and T helper type 2 cells, activated CD4+ T cells, central memory CD8+ T cells, and memory B cells across multiple types of cancer." (PMID 39931080, 2025).
cancer (continued). "Tregs, commonly known as CD4+CD25+Foxp3+, make up approximately 5% of the T‐cell population and diminish antitumor immunity by allowing cancer cells to evade the antitumor response." (PMID 40105652, 2025). "Numerous clinical studies have indicated that extensive infiltration of both CD4+ and CD8+ T cells is correlated with favorable prognosis in multiple cancer types." (PMID 40277945, 2025). "We found that TRIP13 was negatively correlated with poor immune infiltration, especially with CD4 and CD8, in most types of cancers." (PMID 40441196, 2025). "Conversely, in most cancer types, elevated DSN1 expression was negatively correlated with CD4+ T cell recruitment (step 4), macrophage recruitment (step 4), and Th17 cell recruitment (step 4)." (PMID 40535813, 2025). "Relative to the control group, treatment with EPZ015666 led to a significant rise in both the proportion and count of CD4+ T and CD8+ T cells within the cancer microenvironment." (PMID 41463372, 2025). "Single-cell studies of the TME across various cancers have shown an enrichment of CD8 + stress-reactive (STR) cells and CD4 + TSTR cells in RCC patients following ICB therapy." (PMID 41035074, 2025). "As anticipated, cancer tissues rich in ADAMDEC1-positive CAFs also contained significantly higher counts of CD3(+), CD4(+), and CD8(+) T cells." (PMID 40759242, 2025). "Further, TGF‐β1 has been shown to inhibit the proliferation and differentiation of CD4+ and CD8+ lymphocytes, thereby facilitating cancer cell growth." (PMID 40512151, 2025). "VLPs are engineered as prophylactic anti-cancer agents by producing a humoral immune response in vivo and activating CD8+ cells and CD4+ cells which triggers B cells and macrophages." (PMID 40943226, 2025). "The curative effect of IL2 in cancer treatment is dose-dependent, but the main challenge of IL2 in terms of its use as a cancer immunotherapy was that it affects both CD8+ T cells and CD4+Foxp3+ Tregs." (PMID 41050655, 2025). "This is particularly relevant given the well-established role of the CD4 +/CD8 + T cell ratio in predicting immune competence and outcomes in cancer patients." (PMID 41387645, 2025). "Under cancerous conditions, increased HOPX was detected in CD4+ and CD8+ T cells, and HOPX overexpression in cancer cells is significantly related to CD8+ T cell infiltration in the TME." (PMID 41227363, 2025). "We found that the expression of CD3, CD4, CD8, CD20, IL-1β, PD-L1 and TCF-1 in the cancer nest increased after H101 injection during the first recurrence." (PMID 40661951, 2025). "After the second recurrence, the expression of CD3, CD4, CD8, CD20 and IL-1β increased and the expression of PD-L1 and TCF-1 decreased in the cancer nest after H101 injection." (PMID 40661951, 2025). "Together, these findings demonstrate that the differentiation of CD4+ T cells into effector subsets, such as Th1-like, cytotoxic, and CXCL13+ Th cells, is critical for the success of cancer immunotherapies." (PMID 40634636, 2025). "This suggested that cancer cells were sending similar signals to upregulate similar pathways in CD8+ NKT-like cells and memory CD4+ T cells." (PMID 40906153, 2025). "CD4+ TEM, CD4+ naïve T cells, and CD8+ cytotoxic T cells exhibited progressive enrichment from cancer-adjacent to primary tumors and metastatic tissues, suggesting their potential involvement in antitumor responses." (PMID 41246350, 2025). "The synergistic interaction between HIV and HPV accelerates disease progression, as HIV-induced CD4 depletion enhances HPV replication and integration into host DNA, leading to higher rates of invasive cancer." (PMID 41573453, 2025). "Despite these variations, studies carried out in cancer mouse models revealed a connection between B. pesudolongum and an increase in IFN‐γ produced by CD4+ and CD8+ T cells." (PMID 40606779, 2025).